SNORD112 (small nucleolar RNA, C/D box 112)
Synonyms: 14q(0)
Gene: Small nucleolar RNA gene on chromosome 14 (100,897,920 to 100,897,996, forward strand). Ensembl gene ENSG00000275662.
Gene Ontology:
Biological process: RNA processing
Cellular component: nucleolus
Homologues: Orthologues: chimpanzee SNORD112 (100% identical), macaque SNORD112 (99% identical), pig SNORD112 (90% identical), rabbit SNORD112 (81% identical).
Diseases named in the same sentence as SNORD112 in open-access papers:
SNORD112 is named in the same sentence as 3 diseases in open-access papers, as found by Europe PMC text mining. Sharing a sentence is not in itself a finding about the gene and the disease. The quoted sentences say what the papers report.
acute promyelocytic leukemia (3 papers, 2018 to 2023). An aggressive form of acute myeloid leukemia (AML), characterized by arrest of leukocyte differentiation at the promyelocyte stage, due to a specific chromosomal translocation t(15;17) in myeloid cells. "A specific small nucleolar RNA (snoRNA) profile has been reported in acute promyelocytic leukemia (APL) with ectopic expression of SNORD112, SNORD113 and SNORD114 snoRNA clusters." (PMID 30386687, 2018).
breast carcinoma (1 paper, 2024). "Next, we studied the expression levels of MEG8 and SNORD112 in a panel of three different breast cancer cell lines: T47D, MDA-MB-468 and MDA-MB-231; and we also include the non-tumorigenic cell line of epithelial breast tissue MCF10A." (PMID 39706842, 2024).
viral infections (1 paper, 2023). "However, the precise role of SNORD112 and its involvement in viral infections remains open for investigation." (PMID 37664632, 2023).